SEBOX (SEBOX homeobox)
Description:
Probable transcription factor involved in the control of specification of mesoderm and endoderm.
Synonyms: OG9X; OG9; OG-9
Tractability: No criterion of Open Targets' tractability assessment is met for any kind of drug.
Gene: Protein-coding gene on chromosome 17 (28,363,506 to 28,365,199, reverse strand). Ensembl gene ENSG00000274529.
Subcellular location: Nucleus
Gene Ontology:
Molecular function: DNA-binding transcription factor activity; DNA binding
Biological process: regulation of transcription by RNA polymerase II
Cellular component: nucleus
Genetic constraint (gnomAD): Loss-of-function variants: 13 observed, 11.2 expected, observed/expected ratio (o/e) 1.16, 90% interval 0.75 to 1.77. The upper end of that interval is the gene's LOEUF score, 1.77, which puts it in group 6 of 6, group 1 being the genes least tolerant of losing a copy. Missense variants: 227 observed, 222.34 expected, observed/expected ratio (o/e) 1.02, 90% interval 0.92 to 1.14. Synonymous variants: 90 observed, 86.5 expected, observed/expected ratio (o/e) 1.04, 90% interval 0.88 to 1.24.
Homologues: Orthologues: chimpanzee SEBOX (95% identical), pig SEBOX (71% identical), rabbit SEBOX (68% identical), guinea pig SEBOX (64% identical), mouse Sebox (62% identical), rat Sebox (62% identical), zebrafish sebox (30% identical), tropical clawed frog sia1 (18% identical), tropical clawed frog sia2 (17% identical), tropical clawed frog sia3 (17% identical). Paralogues in human: PROP1 (30% identical), ARX (27% identical), ESX1 (25% identical), RAX (24% identical), MIXL1 (24% identical), PAX3 (24% identical), PAX7 (24% identical), PHOX2A (23% identical), PHOX2B (23% identical), UNCX (23% identical), ALX3 (23% identical), ALX4 (23% identical), and 38 more.
Diseases named in the same sentence as SEBOX in open-access papers:
SEBOX is named in the same sentence as 3 diseases in open-access papers, as found by Europe PMC text mining. Sharing a sentence is not in itself a finding about the gene and the disease. The quoted sentences say what the papers report.
metastatic tumors (1 paper, 2025). "While the transcriptomic alterations were generally limited, in bone and lung metastatic tumors, the AA genotype was enriched with SEBOX and ZNF177 expression." (PMID 40282446, 2025).
SEBOX also shares sentences with these, for which no sentence is quoted: lung (1 paper); thyroid cancer (1).